BST2 (bone marrow stromal cell antigen 2)
Diseases named in the same sentence as BST2 in open-access papers (continued):
Sharing a sentence is not in itself a finding about the gene and the disease.
infection (continued). "We observed that knocking down the expression of BST2 increased the replication of PRRSV at 12 and 24 h post infection (hpi); however, the replication of PRRSV was not significantly different between cells transfected with siRNA NC and siRNA BST2 at 36 hpi, as indicated by western blotting results." (PMID 37495116, 2023). "The transmembrane domain of BST2 is another target for viruses, as a mutant BST2 lacking the transmembrane domain could bypass the countermeasures of SARS-CoV-2 and impair its infection." (PMID 35631059, 2022). "Infection with WT HIV-1 resulted in an ∼30% decrease in surface CD47 levels on infected cells compared to bystander GFP cells or cells infected with dU HIV-1, suggesting that modulation of CD47 by Vpu did not involve BST2." (PMID 34425695, 2021). "However, unlike BST2, BST2CV5 did not inhibit foci formation at low MOI infection." (PMID 23236425, 2012).
cancer (82 papers, 2007 to 2026). A tumor composed of atypical neoplastic, often pleomorphic cells that invade other tissues. "Database searches indicated that NAT1, BIRC3, EZH2, MAD2L1, ATP2A3, HMGA1, and BST2 are cancer-associated genes." (PMID 41255601, 2025). "The analysis of other cancers also demonstrated that BST2 was strongly associated with immune cell infiltration and immune response-related molecules." (PMID 36594082, 2023). "According to recent reports, both CAV1 and BST2 are highly associated with the cell proliferation and metastasis of different cancers 24-26." (PMID 36594082, 2023). "Further, several studies have shown that overexpression of BST2 is also associated with tumor progression in different cancers like oral cavity, breast, and endometrial cancer." (PMID 31957537, 2020). "Higher expression of BST-2 has been implicated in the growth and progression of cancers due to its ability to promote cell-to cell interactions and to activate NF-kB-mediated signal transduction pathways." (PMID 30816279, 2019). "Together, our results suggest that reduction in BST-2 expression renders cancer cells anoikis-susceptible." (PMID 30514852, 2018). "Further analyses show that adhesion of cancer cells expressing different levels and variants of BST-2 increases when shBST-2 monolayers are forced to express BST-2D but not BST-2M." (PMID 28300825, 2017). "Induction of BST-2 in macrophages with the BST-2 agonist, IFNα,12 results in increased adherence of cancer cells expressing the different variants of BST-2 to IFNα+ macrophages compared with IFNα- macrophages (white and gray backgrounds)." (PMID 28300825, 2017). "It has been suggested that increased cancer cell adhesion and resistance to apoptosis in vitro is linked to BST-2 expression." (PMID 25499888, 2014). "Four genes showed significant methylation-expression association in all five individual cancer types, BST2, SLA2, GSTT1, and GSTM1." (PMID 23742247, 2013). "Among these, NAT1, BIRC3, EZH2, MAD2L1, ATP2A3, HMGA1, and BST2 are known cancer-associated genes." (PMID 41255601, 2025). "A strong positive association was found between BST2 levels and advancing cancer stage." (PMID 41281378, 2025). "BST2 expression has been associated with cancer progression and invasiveness." (PMID 39020402, 2024). "In addition, it has been suggested that increased immune cell adhesion and resistance of cancer cells to tamoxifen-induced apoptosis is linked to BST-2 expression." (PMID 32155736, 2020). "BST2, which encodes a type II integral membrane protein that inhibits the release of enveloped viruses through its homodimerization, is overexpressed in multiple cancers including breast cancer." (PMID 30655550, 2019). "Our results further suggest that loss of BST-2-conferred anoikis susceptibility may render cancer cells less invasive since the suspended cells were unable to re-adhere." (PMID 30514852, 2018). "It is possible that in vivo, BST-2 may be induced by IFNs released from cancer-associated macrophages (CAMs) or myeloid cells that are part of these clusters." (PMID 30514852, 2018). "Whether BST-2 is directly linked to cancer cell clustering and survival in human blood is yet to be determined." (PMID 28300825, 2017). "It has recently been shown that RING-type E3 ubiquitin ligase, BCA2/Rabring7 (Breast cancer-associated gene 2), a cellular cofactor of BST2 contributes to the restriction of HIV-1 particle production by accelerating the internalization and degradation of viral particles." (PMID 22072966, 2011). "Both assays indicate that viability of shBST-2 cells was significantly reduced under anchorage-independent conditions compared to shCTL cells that survived this condition, indicating that reduction in BST-2 levels may render cancer cells susceptible to anoikis as previously shown in 4T1 cells." (PMID 30514852, 2018). "In cancer, BST2 expression is frequently upregulated through promoter hypomethylation and transcriptional activation." (PMID 41595667, 2026).
cancer (continued). "Liu and colleagues revealed that in a human cancer cell line (SiHa) derived from cervical squamous cell carcinoma, BST2 inhibition reduced SiHa cell viability, migration, and invasive capacity." (PMID 41281378, 2025). "Machine learning analysis pinpointed 14 feature genes, among seven were associated with cancer (NAT1, BIRC3, EZH2, MAD2L1, ATP2A3, HMGA1, and BST2)." (PMID 41255601, 2025). "Conversely, BST2 overexpression in the cancer cells prompted an upregulation of these immunosuppressive factors." (PMID 41281378, 2025). "qRT-PCR analysis of these Tregs revealed that BST2 knockdown in the cancer cells led to a significant downregulation of the key Treg functional markers Foxp3 and IL-10." (PMID 41281378, 2025). "We here introduce a chemical probe closely resemblingthe structural and stereochemical features of NCA and unravel bonemarrow stromal antigen 2 (BST-2) as one of the targets responsiblefor the antiproliferative effect of NCA in cancer cells." (PMID 38818080, 2024). "Literature shows that many cancer types express de novo, or overexpress, IR ligands (such as BST2, PCNA, CAECAM-1 and modified surface carbohydrates) which often represent a strong predictor of poor outcome and metastasis." (PMID 38504978, 2024). "BST2 homodimer promotes cancer cell adhesion and enhances cancer cell survival and growth by enhancing proteasomal degradation of pro-apoptotic proteins." (PMID 35432482, 2022). "Generally, the long isoform and the short isoform of BST2 are alternatively translated at an 1:1 ratio in a variety of cancer cell lines as well as in human CD4 T cells." (PMID 36232695, 2022). "Embedment of cancer cells in the basement membrane matrix reveals that downregulation of BST2 shows invadopodia formation, extracellular matrix degradation, and subsequent cell invasion." (PMID 33879231, 2021). "The inverse effect of DNA methylation on BST-2 expression has been shown previously in the context of cancer and autoimmune studies." (PMID 34025670, 2021). "LILRA4 recognizes the restriction factor human bone marrow stromal cell antigen 2 (BST2, also known as tetherin and CD317), which is upregulated in cancer and HIV-infected cells." (PMID 34594332, 2021). "Our published characterization and functions of BST-2 highlighted a huge potential for inhibiting BST-2 in cancer cells as an attractive anti-cancer strategy." (PMID 32872253, 2020). "One such novel cancer cell adhesion regulator is BST-2, a type II transmembrane protein of 180 amino acids." (PMID 32155736, 2020). "Bone marrow stromal cell antigen 2 (BST2), expressed by several human cancer cell lines, has been identified as the physiological ligand of ILT7 that inhibits the transcription and secretion of I-IFN and other pro-inflammatory cytokines by pDCs." (PMID 32054102, 2020). "The ILT7 ligand BST2, is endogenously expressed by a variety of human cancer cells and inhibits I-IFN production by CpG." (PMID 32054102, 2020). "The BST-2-mediated inhibition of virus release and promotion of cell-cell virus spread is an example of the paradoxical role played by BST-2 in infected cells that is analogous to the role of BST-2 in regulating cancer cell adhesion." (PMID 32155736, 2020). "BST2, a type II transmembrane protein, is known to be involved in the invasion of cancer cells by regulating different signaling pathways and effector proteins." (PMID 31957537, 2020). "Since BST2 is known to be involved in invasion, migration, and growth of different cancer cells, it would be interesting to find out the role of BST2 in IFN-γ-dependent invasion of the trophoblast cells." (PMID 31957537, 2020). "Our research group has been involved in the development of BST-2-based inhibitors of adhesion-driven processes in cancer cells." (PMID 32872253, 2020). "Aside from the interaction with BST-2, membrane binding is critical for specific targeting and functions of peptides with anti-cancer activities." (PMID 32155736, 2020).
cancer (continued). "The authors suggested that BST2 can be a useful target for combined antiangiogenic cancer therapies, since cancer cells can experience nutrient deprivation during progression and/or treatments that disrupt vascularization." (PMID 31991677, 2020). "The effect of B49Mod1 on immune cell to cancer cell adhesion is partly BST-2-independent since adhesion of monocytes to shBST-2 was also inhibited by the peptide (shaded area)." (PMID 29523843, 2018). "Dissemination of cancer cells was significantly inhibited by suppression of BST-2 expression as observed in 4T1 shBST-2 injected mice relative to 4T1 shCTL mice." (PMID 30514852, 2018). "We observed significant inhibition of cancer cell adhesion by B49Mod1 at 4 h that paralleled inhibition observed when BST-2 was shRNA-suppressed in these cells." (PMID 29523843, 2018). "Bone marrow stromal antigen 2 (BST-2) also known as Tetherin has been implicated in the growth and progression of many cancers." (PMID 29523843, 2018). "BST-2 is one such factor that have been shown to be important for cancer aggressiveness, including enhanced metastasis." (PMID 30514852, 2018). "We have demonstrated that inhibitors of MEK1/2 restore the production of IFN-I inhibited by ligation of RRs with HCV particles or with BST2 expressing cancer cells." (PMID 29535732, 2018). "To more closely examine the effect of B49Mod1, we compared B49Mod1-mediated inhibition of cancer cell adhesion with the inhibition obtained with shRNA-mediated BST-2 suppression." (PMID 29523843, 2018). "To evaluate the role of BST-2 in the migration and re-attachment of anchorage-independent cancer cells, we developed a tandem survival-migration-adhesion assay." (PMID 30514852, 2018). "Collectively, our findings highlight BST-2 as a key factor that allows cancer cells to invade, survive in circulation, and at the metastatic site." (PMID 30514852, 2018). "Elevated BST-2 expression regulates cancer cell behavior, such as increased adhesion, anchorage independent growth, survival, migration, and invasion." (PMID 29299143, 2017). "On the basis of these observations, we propose a new model for cancer cell survival and growth in which dimeric BST-2 orchestrates pro-adhesive and anti-anoikis stimuli." (PMID 28300825, 2017). "We found that cancer cells expressing dimeric BST-2 efficiently adhere to other cancer cells, potential stromal cells, and ECM proteins." (PMID 28300825, 2017). "We found that substitution of BST-2 cytoplasmic tail tyrosine residues with alanine residues impair cancer cell motility and invasiveness." (PMID 29299143, 2017). "To further evaluate the significance of BST-2-mediated adhesive interactions, we show that adhesion between monolayers of Cal51 or MDA-MB-231 and several strains of fibroblasts significantly upregulates BST-2 expression in the cancer cells." (PMID 28300825, 2017). "To determine the role of activated BST-2 in cancer cells, we started by investigating the level of GRB2 – a docking protein that binds to phospho-tyrosine residues of activated receptors and recruits ERK1/2 to the signaling complex." (PMID 28300825, 2017). "In contrast, immunoprecipitation with anti-BST-2 antibody reveals that BST-2 is tyrosine phosphorylated in cancer cells in a manner that is dependent on BST-2 dimerization." (PMID 28300825, 2017). "If BST-2 dimerization is involved in protection of cancer cells from anoikis, cells expressing BST-2D will survive under anoikis conditions." (PMID 28300825, 2017). "Mutational analysis identifies the cytoplasmic tail of BST-2 as a novel regulator of cancer cell motility, because cell motility was significantly abrogated by substitution of the BST-2 cytoplasmic tail tyrosine residues to alanine residues." (PMID 29299143, 2017). "Suppression of BST-2 expression reprograms tumorigenic properties of cancer cells and diminishes cancer cell aggressiveness." (PMID 28300825, 2017).
cancer (continued). "We identify BST-2/GRB2/ERK/BIM/Cas3 as the pathway regulating BST-2-mediated cancer cell adhesion, anoikis resistance, anchorage-independency, cell survival and growth." (PMID 28300825, 2017). "It remains to be determined how BST-2 mediates the adhesion of cancer cells to components of the ECM." (PMID 28300825, 2017). "Our data show that the cysteine residues in the extracellular domain (ECD) of BST-2 are required for cancer cells to resist anoikis and for tumors to grow." (PMID 28300825, 2017). "Results show that BST-2-expressing incoming cancer cells efficiently adhere to monolayers of shCTL cells compared with BST-2-suppressed cells." (PMID 28300825, 2017). "In all of these cancer subtypes, the level of the antiviral innate immunity factor BST-2 is elevated." (PMID 29299143, 2017). "The significance of BST-2 dimerization was further appreciated in experimental settings where adhesive interactions of cancer cells with other cells were examined." (PMID 28300825, 2017). "Together, these data are consistent with previous reports that BST-2 promotes proteolytic cancer cell motility." (PMID 29299143, 2017). "BST2 expression affects cancer cell behavior, retains budding viruses to the cell plasma membrane, and inhibits virus replication." (PMID 27359105, 2016). "Despite the functions of BST-2 in breast oncogenesis, little is known about the regulation of BST-2 expression in cancer cells." (PMID 25860442, 2015). "To understand the spectrum of BST-2 expression in various cancers, we analyzed the expression pattern of BST-2 mRNA in various tumors across the TCGA." (PMID 25860442, 2015). "BST-2 demethylation is significantly more prevalent in primary tumors and cancer cells than in normal breast tissues or normal mammary epithelial cells." (PMID 25860442, 2015). "Analysis of the stromal cells for BST-2 and A3G expression confirmed that cancer epithelial cells are the source of elevated BST-2 in tumors." (PMID 25860442, 2015). "We found that cancer cell BST-2 facilitated cancer cell adhesion to fibroblasts as revealed by confocal microscopy and Image J quantification of PKH67Green + cells adhered to MEFs." (PMID 25499888, 2014). "Consistent with the PKH67Green result, suppression of BST-2 decreased the ability of cancer cells to adhere to supporting cells." (PMID 25499888, 2014). "Implantation of BST-2-expressing 4T1 or E0771 cells into syngeneic BALB/c or C57BL/6 mice respectively revealed that BST-2 in cancer cells is disease modifying." (PMID 25499888, 2014). "To further evaluate the role of BST-2 in cancer cell migration, we employed commercially available Boyden chamber assays." (PMID 25499888, 2014). "Intriguingly, we found that the cellular mechanisms responsible for the tumorigenic potential of BST-2 include alterations in cancer cell adhesion, anchorage-independency, migration, and invasion, but not proliferation." (PMID 25499888, 2014). "In our studies, we used two syngeneic mouse models to allow investigation of the contribution of cancer cell BST-2 in mammary tumorigenesis in different backgrounds in the context of an intact immune system." (PMID 25499888, 2014). "Using BST-2-targeting shRNA (sh137 and/or sh413), we efficiently downregulated BST-2 expression in E0771 and 4T1 cancer cells." (PMID 25499888, 2014). "In vitro, we assessed the effect of carcinoma cell BST-2 knockdown and/or overexpression on adhesion, anchorage-independent growth, migration, and invasion." (PMID 25499888, 2014). "For direct cancer targeting, cell surface markers, such as BST2, are the proverbial “silver bullet” particularly if overexpressed in tumors prone to therapeutic resistance." (PMID 23840623, 2013). "We provide evidence for a direct approach that diminishes aberrant BST2 expression in cancer cells as an early targeting strategy to assist in surmounting resistance to pro apoptotic therapies." (PMID 23840623, 2013).